NSD1 (nuclear receptor binding SET domain protein 1)
Description:
Histone methyltransferase that dimethylates Lys-36 of histone H3 (H3K36me2). Transcriptional intermediary factor capable of both negatively or positively influencing transcription, depending on the cellular context.
Synonyms: ARA267; KMT3B; FLJ22263; SOTOS; SOTOS1; STO
Tractability: Small molecule: a structure with a bound ligand is known; a high-quality ligand is known. Antibody: the Human Protein Atlas places it where antibodies can reach. PROTAC: UniProt records ubiquitination sites on it; ubiquitination databases record sites on it; its protein half-life has been measured; a small molecule that binds it is known.
Target class: Writer; Protein methyltransferase; SET domain; Epigenetic regulator
Gene: Protein-coding gene on chromosome 5 (177,131,787 to 177,300,213, forward strand). Ensembl gene ENSG00000165671.
Subcellular location: Nucleus; Chromosome
Subcellular location (Human Protein Atlas): Nucleoplasm; Cytosol; Plasma membrane
Pathways (Reactome):
Chromatin organization: PKMTs methylate histone lysines
Gene Ontology:
Molecular function: histone H3K36 methyltransferase activity; nuclear androgen receptor binding; protein binding; RNA polymerase II cis-regulatory region sequence-specific DNA binding; transcription coregulator activity; zinc ion binding; chromatin binding; histone H3 methyltransferase activity; histone H4K20 methyltransferase activity; nuclear estrogen receptor binding; nuclear retinoic acid receptor binding; nuclear retinoid X receptor binding; nuclear thyroid hormone receptor binding; transcription corepressor activity; histone H3K36 dimethyltransferase activity; histone methyltransferase activity; nuclear receptor binding
Biological process: positive regulation of DNA-templated transcription; regulation of peptidyl-serine phosphorylation; regulation of RNA polymerase II regulatory region sequence-specific DNA binding; negative regulation of transcription by RNA polymerase II; regulation of DNA-templated transcription; chromatin remodeling
Cellular component: nucleoplasm; chromosome; nucleus
Genetic constraint (gnomAD): Loss-of-function variants: 24 observed, 235.02 expected, observed/expected ratio (o/e) 0.1, 90% interval 0.073 to 0.14. The upper end of that interval is the gene's LOEUF score, 0.14, which puts it in group 1 of 6, group 1 being the genes least tolerant of losing a copy. Missense variants: 2,451 observed, 3,365.4 expected, observed/expected ratio (o/e) 0.73, 90% interval 0.7 to 0.75. Synonymous variants: 1,084 observed, 1,224.3 expected, observed/expected ratio (o/e) 0.89, 90% interval 0.84 to 0.93.
Gene-disease validity (ClinGen):
ClinGen rates the evidence that NSD1 causes each of these diseases.
Sotos syndrome (autosomal dominant): Definitive. Sotos syndrome is a rare multisystemic genetic disorder characterized by a typical facial appearance, overgrowth of the body in early life with macrocephaly, and mild to severe intellectual disability.
Homologues: Orthologues: chimpanzee NSD1 (99% identical), macaque NSD1 (98% identical), pig NSD1 (92% identical), dog NSD1 (91% identical), rabbit NSD1 (91% identical), rat Nsd1 (84% identical), mouse Nsd1 (84% identical), guinea pig NSD1 (82% identical), tropical clawed frog nsd1 (37% identical), zebrafish nsd1a (30% identical), zebrafish nsd1b (28% identical), Drosophila melanogaster Set2 (8% identical), and 17 more. Paralogues in human: NSD2 (23% identical), NSD3 (21% identical), SETD2 (13% identical), ASH1L (10% identical), KMT2A (9% identical), KMT2D (7% identical), KMT2B (7% identical), KMT2C (7% identical), EHMT1 (6% identical), EZH1 (6% identical), EZH2 (6% identical), EHMT2 (6% identical), and 7 more.
Diseases named in the same sentence as NSD1 in open-access papers:
NSD1 is named in the same sentence as 178 diseases in open-access papers, as found by Europe PMC text mining. Sharing a sentence is not in itself a finding about the gene and the disease. The quoted sentences say what the papers report.
Sotos syndrome (132 papers, 2005 to 2026). "Sotos syndrome is caused by heterozygous mutations in the NSD1 gene and is characterized by overgrowth, facial abnormalities, brain anomalies, seizures, and impaired intellectual development." (PMID 41501857, 2026). "A broad NGS panel of genes related to epilepsy and intellectual disability was performed, which resulted positive for a de novo heterozygous mutation of the gene NSD1 (NM_022455.5:C.2954_2955delCT, p.Ser985Cysfs*25) responsible for Sotos syndrome." (PMID 41024235, 2025). "Sotos syndrome, a rare congenital overgrowth condition associated with neurodevelopment delay and congenital defects caused by mutations or deletions in the NSD1 gene, has been sporadically linked to renal abnormalities, including nephrocalcinosis." (PMID 41303235, 2025). "McClelland J reported the presence of primary lymphedema in female patients with Sotos syndrome caused by NSD1 internal mutations." (PMID 40766782, 2025). "Sotos syndrome is a rare overgrowth disorder caused by pathogenic variants in the NSD1 gene, characterized by excessive growth in infancy, distinctive facial features, and developmental delay." (PMID 41024235, 2025). "Sotos syndrome is caused by a heterozygous pathogenic variant in the NSD1 gene, which occurs de novo in over 95% of cases." (PMID 41303235, 2025). "The importance of Nsd1 in (epi)genomic regulation is also supported by its recurrent mutations and deregulation in a wide range of human diseases such as Sotos syndrome, Weaver syndrome, and pediatric leukemias." (PMID 40118455, 2025). "The prevalence of NSD1 mutations in Sotos syndrome patients also suggests a critical involvement of NSD1 in the regulation of normal development." (PMID 40118455, 2025). "Identification of a pathogenic variant in NSD1 enables differentiation of a case of Sotos syndrome from other potential OGID diagnoses." (PMID 41153407, 2025). "Sotos syndrome-associated NSD1 variants are most commonly truncating intragenic variants although microdeletions occur in ~10% of cases and missense variants in about a quarter." (PMID 41153407, 2025). "Comprehensive gene panel analysis identified a de novo mutation in the NSD1 gene (c.3439G > T, p.(Glu1147*)), confirming a diagnosis of Sotos syndrome." (PMID 41024235, 2025). "Recently, we have identified a family with mild Sotos syndrome and intrafamilial phenotypic variability associated with a germline NSD1 pathogenic variant." (PMID 41153407, 2025). "Germline haploinsufficiency of NSD1 is implicated as the etiology of Sotos syndrome; however, the underlying mechanism remains far from being clear." (PMID 40118455, 2025). "Sotos syndrome, resulting from pathogenic variants in the NSD1 (Nuclear Receptor Binding SET Domain Protein 1) gene, is also characterized by overgrowth, advanced bone age, macrocephaly, and intellectual disability." (PMID 40922349, 2025). "To assess the potential functional relevance of differentially methylated regions, we identified DMBs (and their associated genes) that were significantly altered in NSD1 exon 3 deletion cases (n = 3) and/or participants with Sotos syndrome (n = 8)." (PMID 41153407, 2025). "In fact, the Sotos syndrome-associated NSD1 missense mutations are enriched at a C-terminal region that encodes the NSD1 PHD1-4, PWWP2, SET, and PHD5-C5HCH, highlighting a functional significance of these domains." (PMID 40118455, 2025). "Most cases of Sotos syndrome are caused by haploinsufficiency of the NSD1 gene (5q35) which encodes nuclear receptor-binding SET Domain protein 1, a lysine-specific histone methyltransferase that has a critical role in epigenetic regulation." (PMID 41153407, 2025). "In this study, we describe an infant in pineoblastoma with facial anomalies, learning disability and mild autism at 1 years diagnosed as Sotos syndrome owing to carrying a novel mutation de novo germline NSD1 likely pathogenic variant." (PMID 38459438, 2024).
Sotos syndrome (continued). "This study aims to elucidate two distinct fetal ultrasound features associated with aberrant brain sulcus formation as potential prenatal markers for Sotos syndrome caused by mutations in the NSD1 gene." (PMID 39425694, 2024). "The diagnosed of Sotos syndrome was confirmed based on the identification of a novel mutation de novo germline NSD1 likely pathogenic variant." (PMID 38459438, 2024). "Pathogenic variants of NSD1 have been identified in Sotos syndrome, which is characterized by overgrowth and learning disabilities." (PMID 38419783, 2024). "A recent report from China described the case of a 4-year-old female child with Sotos syndrome caused by an NSD1 gene nonsense mutation who showed typical facial features, hand deformities, and seizure." (PMID 38673476, 2024). "We used fibroblast cell line fibroblasts cell lines because they were used as in vitro model for patients carrying NSD1 mutation affected by Sotos Syndrome." (PMID 39336709, 2024). "Sotos syndrome is a rare disorder caused by a microdeletion of nuclear receptor-binding set domain protein 1 (NSD1) found on 5q35." (PMID 39224745, 2024). "The diagnosis of Sotos syndrome can be confirmed through molecular genetic testing that identifies a heterozygous NSD1 pathogenic variant or deletion NSD1 in the proband." (PMID 38459438, 2024). "Heterozygous variants of the NSD1 gene encoding a histone methyltransferase located on chromosome 5q35 have been identified as the cause of Sotos syndrome." (PMID 38535015, 2024). "In this study, we analyzed the prevalence of cardiac anomalies, the anatomic types, and the genetic characteristics of 45 patients with Sotos syndrome carrying pathogenetic variants of NSD1 or a 5q35 deletion encompassing NSD1." (PMID 38535015, 2024). "Sotos syndrome (SoS) is a rare overgrowth genetic disease caused by intragenic mutations or microdeletions of the NSD1 gene located on chromosome 5q35." (PMID 38434199, 2024). "The donor and acceptor splice site variants typically lead to loss-of-function of the protein, with loss-of-function variants in NSD1 being associated with Sotos syndrome." (PMID 38459438, 2024). "Other examples highlighted by our analysis include 2 large genes, ARID1B (associated with Coffin-Siris syndrome, MIM #135900) and NSD1 (associated with Sotos syndrome, MIM #117550), which have 13 and 31 pLoFs in UKB, respectively." (PMID 38671509, 2024). "Germline mutations of NSD1 are associated with Sotos syndrome, characterized by distinctive facial features, overgrowth, and developmental delay." (PMID 38459438, 2024). "These fetuses were diagnosed with Sotos syndrome due to de novo mutations in NSD1 gene, as determined by whole‐exome sequencing (WES)." (PMID 39425694, 2024). "Germline variants in the NSD1 gene are responsible for Sotos syndrome, while somatic variants promote neoplastic cell transformation." (PMID 39336709, 2024). "Germline mutations of NSD1 are associated with Sotos syndrome (OMIM 117550), characterized by distinctive appearance, overgrowth, and developmental delay." (PMID 38459438, 2024). "In the current study, we observed that three fetuses with Sotos syndrome, who had de novo genetic variants in the NSD1 gene, exhibited aberrant brain sulcus formation in the second and third trimesters." (PMID 39425694, 2024). "We studied 45 patients with a clinical diagnosis of Sotos syndrome, confirmed using molecular analysis, including 39 patients carrying a pathogenetic variant of the NSD1 gene (Group 1) and 6 patients with a 5q35 deletion (Group 2)." (PMID 38535015, 2024). "Sotos syndrome can be caused by a heterozygous pathogenic variant in NSD1 or a deletion encompassing NSD1." (PMID 37065762, 2023). "The macrocephaly phenotype associated with NSD1 mutations in Sotos syndrome has variable penetrance as 72–95% of patients present with larger head circumference." (PMID 36845425, 2023).
Sotos syndrome (continued). "The pathogenic haploinsufficiency of the Nuclear receptor Set Domain containing protein 1 gene (NSD1) was found as major cause of Sotos syndrome." (PMID 36970544, 2023). "In humans, heterozygous loss-of-function variants in NSD1 increase skeletal growth in Sotos syndrome, whereas, in mice, homozygous loss of Nsd1 impairs skeletal growth, in part by regulating Sox9 expression in chondrocytes." (PMID 36927955, 2023). "Karyotype, mutation analysis in NSD1 for Sotos syndrome, and chromosome 11p15 analysis (multiplex ligation–dependent probe amplification [MLPA] and methylation) for Beckwith-Wiedemann syndrome were normal." (PMID 36927955, 2023). "Sotos syndrome is a rare genetic disorder caused by haploinsufficiency of the NSD1 (nuclear receptor binding SET domain containing protein 1) gene." (PMID 36833222, 2023). "The mechanism through which loss of function mutations in NSD1 contribute to macrocephaly in patients with Sotos Syndrome and Weaver Syndrome is largely understudied." (PMID 36845425, 2023). "Loss of function mutations in NSD1 are a major cause of Sotos Syndrome which presents with macrocephaly, pre- and postnatal overgrowth, facial dysmorphism, ID, autistic features, developmental delay, and in some cases seizures." (PMID 36845425, 2023). "Heterozygous pathogenic variants in NSD1 are associated with Sotos syndrome (MIM:117550) which is characterized by pre- and post-natal overgrowth, macrocephaly, facial dysmorphisms, developmental delay and tumor susceptibility." (PMID 37166351, 2023). "Germline mutations in the NSD1 gene cause Sotos syndrome (SoS) (OMIM 117550), a rare genetic disease with a prevalence of 1/14.000 births." (PMID 35888078, 2022). "Using DNA methylation data generated from their blood compared to healthy individuals, the authors demonstrated that loss-of-function mutations in NSD1, which cause Sotos syndrome, substantially accelerate epigenetic aging." (PMID 36230787, 2022). "As a proof of principle of the interaction between loss of function in H3K36 methylation and DNA methylation status, a specific genome-wide pattern of DNA hypomethylation associated with NSD1 loss-of-function mutations in Sotos syndrome patients was observed." (PMID 36230787, 2022). "Around 50–75% of Sotos syndrome patients demonstrate mutations in the nuclear-receptor-binding SET domain protein 1 (NSD1) gene or a microdeletion at chromosome 5q35." (PMID 36551837, 2022). "Here, we describe a patient with atypical Sotos syndrome caused by an intragenic mutation of NSD1, a novel splice site variant." (PMID 36379925, 2022). "We review the loss of function mutations of NSD1 in humans that are the main cause of SOTOS syndrome, a disease associated with an increased risk of developing cancer." (PMID 36230787, 2022). "In the Human Gene Mutation Database Professional 2020.4, 564 mutations have been reported in NSD1, 461 of them associated to Sotos Syndrome." (PMID 35186810, 2022). "In humans, several amino acid substitutions, nonsense, and frameshift, of NSD1 cause an overgrowth and macrocephaly known as Sotos syndrome." (PMID 36550402, 2022). "NSD1 displays clear enrichment of pathogenic (red) pLoF (X) variants, consistent with haploinsufficiency of NSD1 resulting in Sotos syndrome." (PMID 34859531, 2022). "The 5q35 microdeletion causing haploinsufficiency of NSD1 has been associated with Sotos syndrome (MIM#117550)." (PMID 36303224, 2022). "Kurotaki and coworkers established that 77% of individuals diagnosed with the Sotos syndrome are genetically characterized with microdeletions or point mutations impacting the entire NSD1 gene." (PMID 36230787, 2022). "Six individuals diagnosed with Sotos syndrome and carrying pathogenic NSD1 mutations were initially tested to confirm the robustness and specificity of the previously identified disease-specific signature." (PMID 36421837, 2022). "Heterozygous pathogenic variants in NSD1 are detected in 70% to 93% of typical Sotos syndrome patients." (PMID 35158968, 2022).
Sotos syndrome (continued). "In a familial case of Sotos syndrome (mother and two children, a son and daughter affected), it was found that a novel NSD1 mutation, C2175S, also caused the condition." (PMID 36551837, 2022). "5q35 deletion is predominantly mediated by NAHR and is associated with Sotos syndrome 1, where haploinsufficiency of the nuclear receptor-binding set domain protein (NSD1) gene contained within this region is shown, on its own, to be causative for Sotos." (PMID 35887210, 2022). "Sotos syndrome is usually caused by haploinsufficiency of NSD1; it is characterized by overgrowth, craniofacial features, and learning disabilities." (PMID 36379925, 2022). "Another gene associated with macrocephaly is the nuclear receptor binding SET domain protein 1 or NSD1, from which mutations result in an overgrowth condition known as Sotos Syndrome." (PMID 36550402, 2022). "Genes associated with macrocephaly have been reported to cause this change, for example NSD1 which causes Sotos syndrome." (PMID 36550402, 2022). "Concerning BAB9637, we classified the de novo duplication encompassing NSD1 associated with Sotos syndrome (MIM#117550) as a pathogenic variant, based on the most recent consensus recommendation of the American College of Medical Genetics and Genomics (ACMG)." (PMID 36303224, 2022). "NFIX1 and NSD1 genes are associated with macrocephaly and Sotos syndrome and were described to be important in the shaping of the modern human head." (PMID 36550402, 2022). "Pathogenic NSD1 mutations have a genome-wide impact on DNA methylation, generating a specific episignature, and are involved in Sotos syndrome, Wolf–Hirschhorn syndrome and different types of cancer." (PMID 36611369, 2022). "Our study analyzed all mutations reported in NSD1 for Sotos syndrome and localized them along on exons and functional domains." (PMID 36550402, 2022). "Sotos Syndrome is caused by heterozygous pathogenic variants in the nuclear receptor SET domain-containing protein 1 (NSD1) gene located on 5q35." (PMID 35186810, 2022). "In the Sotos syndrome, the truncating mutations were spread throughout NSD1, but there was evidence of clustering of missense mutations in highly conserved functional domains." (PMID 36230787, 2022). "The genomic alterations responsible for Sotos syndrome are broadly classified as intragenic variants of NSD1 and 5q35 microdeletions encompassing NSD13." (PMID 36379925, 2022). "Objective: we performed microarray DNAm profiling in a set of 11 individuals with a clinical suspicion of Sotos syndrome and carrying an NSD1 VoUS or previously unreported variants to solve uncertainty in defining pathogenicity of the observed variants." (PMID 36421837, 2022). "In conclusion, we identified a novel splice site mutation of NSD1 in a patient with atypical Sotos syndrome that included substantial connective tissue involvement without overgrowth." (PMID 36379925, 2022). "The occurrence of an APP in Sotos syndrome described here is a novel finding, expanding the spectrum of this NSD1-related over-growth and tumor-predisposition." (PMID 34997889, 2022). "Applying this approach to the remaining 11 individuals with NSD1 variants, we succeeded in confirming pathogenicity in eight subjects and excluding the diagnosis of Sotos syndrome in three." (PMID 36421837, 2022). "For example, while SETD1B variants in the SETD1B-related syndrome result in a strong hypermethylated signature, NSD1 variants associated with Sotos syndrome display remarkable hypomethylation." (PMID 33337535, 2021). "It is similar to Sotos syndrome that is caused by mutations of the nuclear receptor-binding SET domain 1 (NSD1) gene." (PMID 33937229, 2021). "To date, more than 450 Sotos syndrome patients with an NSD1 abnormality have been reported in Human Gene Mutation Database Professional (as of 17 February 2021)." (PMID 34031356, 2021).